RC3H2 (ring finger and CCCH-type domains 2)
Description:
Post-transcriptional repressor of mRNAs containing a conserved stem loop motif, called constitutive decay element (CDE), which is often located in the 3'-UTR, as in HMGXB3, ICOS, IER3, NFKBID, NFKBIZ, PPP1R10, TNF and in many more mRNAs. Binds to CDE and promotes mRNA deadenylation and degradation. This process does not involve miRNAs. In follicular helper T (Tfh) cells, represses of ICOS and TNFRSF4 expression, thus preventing spontaneous Tfh cell differentiation, germinal center B-cell differentiation in the absence of immunization and autoimmunity. In resting or LPS-stimulated macrophages, controls inflammation by suppressing TNF expression. Also recognizes CDE in its own mRNA and in that of paralogous RC3H1, possibly leading to feedback loop regulation (By similarity). miRNA-binding protein that regulates microRNA homeostasis. Enhances DICER-mediated processing of pre-MIR146a but reduces mature MIR146a levels through an increase of 3' end uridylation. Both inhibits ICOS mRNA expression and they may act together to exert the suppression. Acts as a ubiquitin E3 ligase. Pairs with E2 enzymes UBE2B, UBE2D2, UBE2E2, UBE2E3, UBE2G2, UBE2K and UBE2Q2 and produces polyubiquitin chains. Shows the strongest activity when paired with UBE2N:UBE2V1 or UBE2N:UBE2V2 E2 complexes and generate both short and long polyubiquitin chains. Involved in the ubiquitination of MAP3K5. Able to interact with double-stranded RNA (dsRNA).
Synonyms: MNAB; RNF164; FLJ20301; FLJ20713
Tractability: PROTAC: ubiquitination databases record sites on it; its protein half-life has been measured.
Gene: Protein-coding gene on chromosome 9 (122,844,556 to 122,905,513, reverse strand). Ensembl gene ENSG00000056586.
Subcellular location: Cytoplasm, P-body
Subcellular location (Human Protein Atlas): Vesicles
Gene Ontology:
Molecular function: DNA binding; double-stranded RNA binding; RNA binding; RNA stem-loop binding; ubiquitin protein ligase activity; mRNA binding; metal ion binding; protein-RNA sequence-specific adaptor activity
Biological process: protein polyubiquitination; negative regulation of T-helper 17 cell differentiation; nuclear-transcribed mRNA catabolic process, deadenylation-dependent decay; regulation of miRNA metabolic process; T cell receptor signaling pathway; ubiquitin-dependent protein catabolic process; protein ubiquitination
Cellular component: cell surface; cytoplasm; membrane; cytoplasmic stress granule; P-body
Genetic constraint (gnomAD): Loss-of-function variants: 27 observed, 120.53 expected, observed/expected ratio (o/e) 0.22, 90% interval 0.16 to 0.31. The upper end of that interval is the gene's LOEUF score, 0.31, which puts it in group 1 of 6, group 1 being the genes least tolerant of losing a copy. Missense variants: 1,137 observed, 1,454 expected, observed/expected ratio (o/e) 0.78, 90% interval 0.74 to 0.82. Synonymous variants: 505 observed, 510.13 expected, observed/expected ratio (o/e) 0.99, 90% interval 0.92 to 1.07.
Homologues: Orthologues: chimpanzee RC3H2 (99% identical), macaque RC3H2 (99% identical), pig RC3H2 (98% identical), dog RC3H2 (98% identical), guinea pig RC3H2 (97% identical), mouse Rc3h2 (95% identical), rabbit RC3H2 (93% identical), rat Rc3h2 (92% identical), zebrafish rc3h2 (50% identical), Drosophila melanogaster roq (31% identical). Paralogues in human: RC3H1 (49% identical), RNF228 (7% identical), RNF182 (5% identical), RNF227 (3% identical), RNF224 (3% identical).
Diseases named in the same sentence as RC3H2 in open-access papers:
RC3H2 is named in the same sentence as 7 diseases in open-access papers, as found by Europe PMC text mining. Sharing a sentence is not in itself a finding about the gene and the disease. The quoted sentences say what the papers report.
autoimmune (2 papers, 2018 to 2020). "Roquin-2 is encoded by RC3H2 and has been shown to play a key role in posttranscriptional regulation of autoimmunity and inflammatory response." (PMID 33186364, 2020).
cardiovascular disease (1 paper, 2020). "We identified one known locus (ANGPTL4) and four new loci (PLCL1, RC3H2, TMPRSS5, and LDLRAD1) associated with cardiovascular disease risk that warrant further investigation." (PMID 33186364, 2020). "This study identified one known locus (ANGPTL4) and four new loci (PLCL1, RC3H2, TMPRSS5, and LDLRAD1) associated with cardiovascular disease risk that warrant further investigation." (PMID 33186364, 2020).
tumour (1 paper, 2025). "Six hits in five genes [AK3 (rs378117), TRPM3 (rs1329774 and rs4745058), CDH4 (rs2427043), LINC00504 (rs76228864), and GRIN2D (rs76754767)] were associated with a risk of tumour progression, whereas variants in HPGD (rs45593131) and RC3H2 (rs2792999) were suggested as protective factors." (PMID 40535770, 2025).
RC3H2 also shares sentences with these, for which no sentence is quoted: autoimmune disease (1 paper); cancer (1); Mitochondrial myopathy (1); Oral leukoplakia (1).